EGF (epidermal growth factor)
Diseases named in the same sentence as EGF in open-access papers (continued):
Sharing a sentence is not in itself a finding about the gene and the disease.
cancer (continued). "Together, these results demonstrate that the MUC1 intracellular domain is both necessary for EGF-induced carcinoma cell migration on vitronectin and sufficient to drive cell migration on vitronectin and metastasis in the absence of EGF." (PMID 22586492, 2012). "Our results imply that SPHK1 may be the central controller of amplification loops of EGF, AREG and EREG-EGFR interactions that can contribute to cancer progression." (PMID 21936950, 2011). "Therefore, the CXCL12 receptors, CXCR4 and CXCR7, should be thought of as a node that connects multiple loops, including the highly important EGF/HER loops, linking cancer (oncogenes) and inflammation." (PMID 20946648, 2010). "We performed on similar experiment on 25 cancer cell lines and EGF did not stimulate cancer cell proliferation (unpublished data)." (PMID 19456848, 2009). "KGF stimulates cell growth in some cancer cell lines, whereas there is no report of cell growth stimulation by exogenous EGF." (PMID 19456848, 2009). "In addition, an EGF-induced phosphorylation of FAK, yet another essential mediator for cancer cell invasiveness, was markedly inhibited by ENMD-1198." (PMID 18651980, 2008). "The link between HIF-1 and EGF and the reported ability of mTOR inhibitors rapamycin and everolimus to reduce VEGF secretion in vitro and in vivo, renders mTOR inhibitors potentially effective against cancer cells resistant to EGFR inhibitors." (PMID 18319715, 2008). "In in vitro assays, ENMD-1198 substantially abrogated EGF- and HGF-mediated cancer cell migration and invasiveness, suggesting that this substance could be valuable for reducing HCC metastasis." (PMID 18651980, 2008). "As for EGF and HB-EGF, targeting nuclear HMW FGF2s may generate new anti-cancer therapies for patients resistant to classical protocols." (PMID 17049074, 2006). "This study examined the expression of epidermal growth factor (EGF) cell-surface receptors, the response to exogenous ligand and the autocrine production of transforming growth factor alpha (TGF-alpha) in normal and carcinoma-derived human oral keratinocytes." (PMID 8286215, 1994). "Notably, the EGF–EGFR and PI3K/AKT pathways are important for cell survival and proliferation, providing a mechanistic explanation for the antiproliferative effects of statins in cancer cells." (PMID 40832614, 2025). "The complete inhibition of EGF-mediated phosphorylation of the WT indicates the non-specific effect of erlotinib on normal tissues in which wild-type EGFR is expressed when applied in cancer patients." (PMID 40649937, 2025). "Epidermal growth factor (EGF) and EGF receptor-specific peptide (GE11), which binds specifically to EGF receptor, were incorporated onto the surfaces of exosomes that carried miRNA lethal-7 gene (let-7a), to deliver let-7a to EGF receptor-expressing cancer tissue." (PMID 38607173, 2024). "Interestingly, the migration ability of the Tks4-KO cancer cells was slightly reduced both in nontreated and EGF-treated cells." (PMID 38985526, 2024). "The differing responses of the cancer cells may reflect distinct cell cycle states or indicate that the EGF signaling cascade is not expressed or not active in every cell." (PMID 39369027, 2024). "Binding of a ligand of the epidermal growth factor (EGF) family to HER receptors induces receptor dimerization, preferentially with HER2, phosphorylation of HER2, followed by intracellular signals essential for proliferation and survival of HER2 positive cancer cells." (PMID 38834577, 2024). "However, EGF response was not potentiated in drug-treated cancer lines that expressed constitutively active transmembrane ALK mutants." (PMID 39488530, 2024). "Similarly, an open-label, non-comparative, multicentre, phase II trial of 46 cancer patients treated with the EGFR inhibitor erlotinib showed that EGF ointment was effective in treating 69.2% of patients." (PMID 39061166, 2024).
cancer (continued). "Additionally, IQGAP1 stimulates EGF-induced activation of the JAK-STAT pathway, a signaling module where JAK non-receptor tyrosine kinases activate STAT transcription factors to promote expression of critical mediators of cancer and inflammation." (PMID 37071417, 2023). "Moreover, factors like TGFβ, EGF, and FGF secreted by TAMs also skew cancer cells to CSCs." (PMID 38035101, 2023). "Moreover, EGF is a significant regulatory factor that can induce EMT through increasing expression of transcription factors responsible for reducing E-cadherin and promoting cancer invasion." (PMID 37179366, 2023). "In addition, it has been shown that TAMs release EGF, which may induce EMT by activating the EGFR/ERK1/2 signal pathway in cancer cells." (PMID 37211559, 2023). "We analyzed the expression of AQP3, PI3K, and pAkt/Akt as a part of EGFR/PI3K/Akt pathway, as well as NRF2 in three cancer cell lines and nontumorigenic cell line in order to investigate the influence of lipid raft disruption and EGF treatment on these proteins." (PMID 37175840, 2023). "Interestingly, the growth factors (e.g., TGF-beta, PDGF, and EGF) are prominent inducers of EMT, whereas the BDNF/TrkB pathway proved effective modulator of EMT in different cells and cancer progression." (PMID 37645595, 2023). "Additionally, EGF may prevent expression of the long noncoding RNA LIMIT, increasing the capacity for cancer cells to move." (PMID 38033495, 2023). "EGF activates TERT transcription in cancer cells but not in somatic cells." (PMID 37233461, 2023). "TAMs employ this mechanism by producing growth factors like epidermal growth factor (EGF) and fibroblast growth factor (FGF) to facilitate the activation of downstream signaling pathways, subsequently leading to enhanced survival, migration, metastasis, and suppression of apoptosis in cancer cells." (PMID 38035101, 2023). "Additionally, cancer cells lacking the p85α function became more sensitive to EGF than cells with a normal p85α function." (PMID 35482141, 2022). "Various factors such as vascular endothelial growth factor (VEGF), epidermal growth factor (EGF), fibroblast growth factor (FGF), insulin-like growth factor (IGF), and platelet-derived growth factor (PDGF) seem to be responsible for high vascularity and cancer cell proliferation." (PMID 36430594, 2022). "The results support the existence of an EGF-mediated downstream ERK1/2-RSK-rpS6 signalling pathway that bypasses EGFR in the presence of high OTR expression and compromised OTR signalling, which could be a cancer growth or survival adaptation." (PMID 35884900, 2022). "Cancer cells and other TME cells secretes growth factors like transforming growth factor beta (TGF-β), fibroblast growth factor 2 (FGF2), platelet-derived growth factor (PDGF), and epidermal growth factor (EGF) which are key regulators of fibroblast recruitment and activation." (PMID 36253762, 2022). "Although in numerous cancer cell systems, NTS signaling depends on EGFR activation, this is not the case in HT29 cells, since sSortilin/NTSR3 is unable to compete with EGF on the EGFR, and reciprocally, EGF is unable to compete with sSortilin/NTSR3 on its binding sites." (PMID 36233189, 2022). "Transgenic DPP-IV overexpression led to increased EGF-induced colony formation in normal breast epithelial cells and facilitated EGF signaling via MEK/ERK and JNK/c-Jun, leading to the expression of peptidylprolyl cis/trans isomerase-1 (PIN1) and cyclin D1 in cancer cells." (PMID 35565202, 2022). "The conflict in the results from bulk and specific cell population also includes the study of epidermal growth factor (EGFR) that plays a critical role in many cancer types, with its downstream pathways including RAS-MAPK/PI3K-AKT-mTOR pathways that are well studied in cancer prognosis." (PMID 36498893, 2022).
cancer (continued). "It was reported that lovastatin inhibited EGF-induced EGFR autophosphorylation and its downstream signaling, and the combined treatment of gefitinib with lovastatin induced synergistic anti-proliferative and pro-apoptotic effects in cancer cell lines, including NSCLC cells." (PMID 35159223, 2022). "Furthermore, EGF and BMP-4 cooperate to inhibit MMP-9 expression in cancer cells." (PMID 35150338, 2022). "Similarly, SPNS2 has been shown to deliver S1P to S1PR2, leading to increased epidermal growth factor (EGF)-mediated cancer cell invasion, suggesting that SPNS2 inhibitors may be useful therapeutics for cancer treatment." (PMID 35565311, 2022). "Furthermore, NF-κB is involved in various cancers, such as BC, via several stimulators, including various pro-inflammatory cytokines (IL-1β and TNF-α), growth factors (epidermal growth factor [EGF]), DNA-damaging agents (radiation), and oncogenes (rat sarcoma [RAS])." (PMID 35986321, 2022). "Therefore, we do not exclude the possibility for the enhanced anti-cancer effects for the RS mutant by increasing the surface density of conjugated EGF on the nanoparticles." (PMID 34512175, 2021). "Reportedly, several RTKs, including receptors for epidermal growth factor (EGF), hepatocyte growth factor (HGF), platelet-derived growth factor (PDGF), or nerve growth factor, are positively or negatively regulated by the expression of gangliosides in cancer cells." (PMID 34064863, 2021). "In addition to controlling glucose metabolism, PKM2 also regulates hypoxia-inducible factor-1α (HIF-1α), β-catenin (β-cat), epidermal growth factor (EGFR), signal transductors, transcriptional activators 3 (STAT3), and other cancer-related factors, thereby promoting cell growth and proliferation." (PMID 33905408, 2021). "Macrophages can produce proinflammatory mediators such as IL-6, TNF, IFN-γ, growth factors, including epidermal growth factor (EGF) and Wnt, proteases, ROS, and nitrogen substances that may produce a mutagenic microenvironment, further facilitating cancer initiation." (PMID 34965886, 2021). "Several signaling pathways, including hepatocyte growth factor (HGF), epidermal growth factor (EGF), transforming growth factor beta (TGF-β), Notch, and Wnt/β-catenin, regulate EMT, and the activation of Wnt/β-catenin pathway is commonly seen in many malignant tumors." (PMID 34337054, 2021). "Keeping in mind that EGF-mediated EMT is a common feature in several cancers, the use of Spautin-1 as an EGFR signaling inhibitor may prove a promising novel addition to therapeutic schemes for several cancers, including PCa." (PMID 34199763, 2021). "Upon receptor binding, EGF and TGF activate downstream mitogen-activated protein kinase (MAPK) and AKT-mammalian target of rapamycin (mTOR) pathways, which regulate apoptosis and cell proliferation, while inducible nitric oxide synthase (iNOS) modulates cellular bioenergetics pathways in cancer." (PMID 33842373, 2021). "In addition to over-production of EGF and its family members in tumors, EGFR is similarly over-produced, and mutant hyper-active forms of EGFR are uniquely found in some brain, lung, and other cancers." (PMID 34206026, 2021). "In addition, Pelitinib inhibit EGF-induced activation of AKT and ERK1/2 in cancer cells." (PMID 34149925, 2021). "In contrast, EGF-PLGA@5Fu/PFC NPs exhibited slow drug release at pH 7.4, which indicated that EGF-PLGA@5Fu/PFC NPs could rapidly release 5Fu in the acidic conditions common to cancer cells." (PMID 32345258, 2020). "The results of SAHF and β‐gal staining confirmed that EGF treatment could not induce cellular senescence in these cancer cells." (PMID 32323422, 2020). "EGF treatment also did not inhibit cell proliferation in the cancer cells." (PMID 32323422, 2020). "Furthermore, we show the cetuximab-induced EGF secretion to be specific to CAFs and not to cancer cells or normal fibroblasts." (PMID 32481658, 2020).
cancer (continued). "Standard culture media for 2D immortalized cancer cell lines do not contain EGF." (PMID 32481658, 2020). "EGFR signaling in invadopodia might be also sustained by a high level of heparin-binding (HB)-EGF, which is synthesized as pro-HB-EGF and subsequently cleaved by ADAM-12 to release a soluble form binding to EGFR, providing an advantage for cancer cells to intravasate, invade and metastasize." (PMID 33178698, 2020). "The fact that COX2 c.-899G>C, EGF c.382A>G, and EGFR c.1562G>A polymorphisms were not directly associated with cancer risk is not surprising, considering that most of these polymorphic variants are low penetrance risk factors that have a minor influence in protein expression or function." (PMID 32338278, 2020). "These cancers display mutations of the egfr gene in 4–14% of the cases, suggesting that AJ complex-mediated stabilization and genetic alteration may not represent mutually exclusive mechanisms to promote EGF signaling in cancer." (PMID 31015417, 2019). "However, SPINK1 overexpression, which was observed in different types of cancer, may be partially due to SPINK1 having structural homology with the epidermal growth factor." (PMID 31886233, 2019). "Moreover, CSC niches may also produce survival cytokines, such as EGF, FGF, and VEGF, all of which are responsible for the radioresistance and radioprotection of cancer cells." (PMID 31726667, 2019). "EGF is considered as a ligand part of EGFR, and previous studies have demonstrated that its activation could stabilize and enhance the β-catenin nuclear accumulation in cancer." (PMID 31171012, 2019). "Anti-EGFR therapy in the context of cancer treatment may have cardiotoxic side effects, maybe due to EC dysfunction, because EGFR, which is normally involved in EGF/neuregulin signaling, can also form a holoreceptor with NRP1 and elicits a repellent SEMA3D signal in venous ECs." (PMID 30717262, 2019). "Epidermal growth factor (EGF) and Transforming growth factor beta 1 (TGF-β1) act as potent drivers of cancer progression through the induction of epithelial-mesenchymal transition (EMT), in which epithelial cells acquire a mesenchymal phenotype and gain cancer stem-cell-like properties." (PMID 30347648, 2018). "Tailoring the AAb profiling with a systems biology approach provides an excellent image of the network of AAbs targeting proteins which may be key drivers of cancer-interacting SPs such as PLD, PI3K-Akt, MAPK, EGF/EGFR, c-Met, Ras, DDR, IL-4, IL-6, and TGF-β SPs in the NSCLC and SM groups." (PMID 29062084, 2017). "HPßCD-HET0016 treatment was also able to significantly decrease the protein expression of EGF, Fas, and SDF-1α in conjunction with the reduced levels of MMP-2 and -9, and the granulocytic MDSC population result in an overall attenuation of migratory and invasive properties of cancer cells." (PMID 28609459, 2017). "The restoration of other abnormal oncogenic signals in cancer cells, such as in the Wnt-β-catenin, AKT-PI3K-mTOR, and epidermal growth factor (EGF)/EGF receptor (EGFR) signaling pathways, may also be promising strategies for combination immunotherapy approaches." (PMID 28239469, 2017). "Given EGF would activate the PI3K/Akt/mTOR signaling pathway, it is crucial to investigate whether or not MeCDDA can alter the expression level of EGFR on SCLC cells or induce conformational changes in EGF protein structure, achieving its anti-cancer effect." (PMID 28671570, 2017). "It is not clear what role EINCR1 might have in the tumourigenic process but as EINCR1 is a target of the EGF pathway and EGFR-regulated pathways are often activated in cancer cells it appears likely that it might be an important mediator of dysregulated signalling." (PMID 28732076, 2017). "Thus, for motile cancer cells, PI3K/AKT signaling is activated more easily in response to EGF." (PMID 27167206, 2016).
cancer (continued). "In conclusion, the EGF-conjugated HAOA-coated gold nanoparticles developed in this work show a potential application for near infrared (NIR, 650–800 nm) photothermal therapy, which may efficiently destroy cancer cells." (PMID 27788212, 2016). "Flavonoids, caffeic acid, and chlorogenic acid were isolated from Sakhalin bilberry Vaccinium smallii leaves and were studied as cancer-preventive agents; they inhibited epidermal growth factor (EGF)-induced neoplastic transformation of mouse cells, without exerting any toxic effects." (PMID 27258314, 2016). "Importantly, growth factors like the epidermal growth factor (EGF) can stimulate the activity of the POU4F2 promoter and subsequently its mRNA and protein expression, which in turn can affect POU4F2 target genes influencing growth and behavior of cancer cells." (PMID 27923066, 2016). "Studies have reported that heparin-binding EGF (HB-EGF) can bind to EGFR when mediated by sulfated HSPG, thereby promoting sustained phosphorylation of EGFR on Tyr1068 and Tyr992 residues and activating the downstream AKT and ERK signaling pathways to promote cancer cell proliferation and migration." (PMID 27806323, 2016). "Therefore, EGF could induce EMT and cancer cell invasion in MDA-MB-231 cells through the ERK1/2-phospho-Smad2/3-Snail signaling pathway." (PMID 27829223, 2016). "Moreover, these CAFs also showed increased expression of growth factors including fibroblast growth factors (FGFs), epidermal growth factor (EGF) and platelet derived growth factor (PDGF), which have been reported to be upregulated in activated CAFs and contribute to cancer proliferation." (PMID 27528027, 2016). "EGF stimulated AREG production was tightly regulated in normal and transformed cell lines, suggesting that failure to control EGFR induced AREG expression may be a crucial step in carcinogenesis and cancer progression." (PMID 27669890, 2016). "Moreover, it may regulate various molecular targets including EGF, PDGF, VEGF, NF-kB, and STAT3 in cancers." (PMID 26490686, 2015). "EGF induced cancer cell migration in parental but not PTX3-knockdown cells." (PMID 25797258, 2015). "Mechanisms for consideration include cancer cell acidification via action of tetrac/nanotetrac on the Na+/H+ exchanger (NHE1) and hormone analogue effects on calmodulin-dependent processes and on interactions of P-gp with epidermal growth factor (EGF) and osteopontin (OPN), apparently via αvβ3." (PMID 25866761, 2015). "In another example, epidermal growth factor (EGF), which markedly promotes the cell growth of normal epithelial cells and only moderately promotes the growth of cancer cells, actually inhibits the growth of cancer cells when both normal and cancer cells are co-cultured." (PMID 25379014, 2014). "To illustrate this, we have extracted the I/O response RDSP of the PI3K/PTEN/AKT and MAPK pathways for different cancer cell lines using experimental data on the dose dependence of receptor activation (EGFR and PDGFR) and output signal (pAKT and pERK) on ligand concentrations (EGF and PDGF)." (PMID 24551596, 2014). "They release epidermal growth factor (EGF), platelet-derived growth factor (PDGF), tumor transforming growth factor (TGF)-β, vascular endothelial growth factor (VEGF) and other trophic factors that promote cancer cell growth and the cancer vascularization process." (PMID 24324582, 2013). "Glabruquinone A (3-demethylubiquinone Q2, 11) is closely related to the ubiquinones, although lacking the methyl group in the quinoid moiety; it is not a cytotoxin but demonstrated good cancer preventive activity on JB6 Cl 41 cell transformation activated by epidermal growth factor (EGF)." (PMID 23685889, 2013). "Since TACC3 is overexpressed in cervical and other cancers and appears to be a key player in EGF/EGFR-driven EMT process, it is possible that depletion of TACC3 may be a good approach to treat cancers that are driven by EGF/EGFR signaling pathways or resistant to anti-EGFR therapy." (PMID 23936413, 2013).